SCARNA5 (small Cajal body-specific RNA 5)
Synonyms: U87
Gene: Small Cajal body-specific RNA gene on chromosome 2 (233,275,727 to 233,276,002, forward strand). Ensembl gene ENSG00000252010.
Gene Ontology:
Biological process: RNA processing
Cellular component: nucleolus
Diseases named in the same sentence as SCARNA5 in open-access papers:
SCARNA5 is named in the same sentence as 3 diseases in open-access papers, as found by Europe PMC text mining. Sharing a sentence is not in itself a finding about the gene and the disease. The quoted sentences say what the papers report.
Crohn disease (1 paper, 2022). A gastrointestinal disorder characterized by chronic inflammation involving all layers of the intestinal wall, noncaseating granulomas affecting the intestinal wall and regional lymph nodes, and transmural fibrosis. "In humans, 16 different single nucleotide variants (SNPs) located within the Atg16l1 gene and in an intergenic region between the Atg16l1 and Scarna5 genes have been associated with inflammatory bowel disease, ulcerative colitis, and Crohn’s disease." (PMID 35509963, 2022).
SCARNA5 also shares sentences with these, for which no sentence is quoted: inflammatory bowel disease (1 paper); ulcerative colitis (1).